LINC01273 (long independently transcribed non-coding RNA 1273)
Gene: Long non-coding RNA gene on chromosome 20 (50,165,586 to 50,188,316, forward strand). Ensembl gene ENSG00000231742.
Diseases named in the same sentence as LINC01273 in open-access papers:
LINC01273 is named in the same sentence as 2 diseases in open-access papers, as found by Europe PMC text mining. Sharing a sentence is not in itself a finding about the gene and the disease.
LINC01273 shares sentences with these, for which no sentence is quoted: COVID-19 (1 paper); tumor (1).